VDR (vitamin D receptor)
Diseases named in the same sentence as VDR in open-access papers (continued):
Sharing a sentence is not in itself a finding about the gene and the disease.
prediabetes (6 papers, 2022 to 2026). "The biggest novelty of this study is the target people with prediabetes and their VDR polymorphisms interaction effect." (PMID 37845735, 2023). "In this study, we investigated the association between 25(OH) vitamin D levels, vitamin D-binding protein, and VDR polymorphisms in subjects with prediabetes and T2D in a mixed-ancestry South African population, as research is lacking in this population group." (PMID 35956323, 2022). "Additionally, the relationship in prediabetes is modified by VDR polymorphisms, and improved triglyceride levels contribute partially to this favorable association." (PMID 41409610, 2025). "However, whether the modification effect of VDR polymorphisms maintained for individuals with prediabetes is unclear." (PMID 37845735, 2023).
primary hyperparathyroidism (6 papers, 2009 to 2026). "A meta-analysis was possible for VDR rs1544410 gene polymorphism in patients with ESRD and CaSR rs1801725 gene polymorphism in patients with primary hyperparathyroidism." (PMID 29794776, 2018).
prostate tumors (6 papers, 2014 to 2025). "The high expression of VDR in prostate tumours reduces the risk of lethal cancer." (PMID 29659618, 2018). "Vitamin D has also inhibitory functions affecting the growth of colon, breast and prostate tumor cells via the vitamin D receptor (VDR)." (PMID 36432621, 2022). "For example, some indications have emerged that prostate tumors with high levels of vitamin D (1,25-dihydroxyvitamin D3) receptors (VDR) are twice as likely to be TMPRSS2-ERG fusion-positive than those with the low VDR levels." (PMID 24739220, 2014). "A recent study showed that high calcium-sensing receptor (CaSR) expression in primary prostate tumors was associated with lethal progression of the disease if the tumors expressed low vitamin D receptor (VDR) levels, but not if the tumors had high VDR levels." (PMID 27803671, 2016).
RSV bronchiolitis (6 papers, 2016 to 2023). "VDR SNPs have been associated with severe RSV bronchiolitis and vitamin D pathway has been related to the severity of SARS-CoV-2 infection." (PMID 34226633, 2021). "In the RSV bronchiolitis study and contrasting to our study, however, the less pro-inflammatory minor allele of the VDR SNP occurred at a higher frequency in the RSV patients’ cohort compared to the control population group." (PMID 26894582, 2016). "The different pathogenic mechanisms in pertussis, TB and RSV bronchiolitis may explain in part the opposing VDR SNP associations found with host susceptibility to respiratory disease." (PMID 26894582, 2016).
systemic sclerosis (6 papers, 2015 to 2024). A chronic disorder, possibly autoimmune, marked by excessive production of collagen which results in hardening and thickening of body tissues. "A similar mechanism was described in the context of systemic sclerosis wherein primary human skin fibroblasts treated with the VDR agonist paricalcitol, ligand-bound VDR associated with phosphorylated SMAD3 to inhibit downstream gene transcription." (PMID 26061181, 2015). "VDR knockdown enhances fibroblast sensitivity to TGF-β1 in patients with systemic sclerosis, and activation of VDR with paricalcitol reduces the stimulatory effect of TGF-β1 on fibroblasts, and so inhibits collagen production and myofibroblast differentiation." (PMID 32039229, 2019). "It was observed that VDR expression is decreased in lesional skin, in fibroblasts of systemic sclerosis (SSc) patients, and in fibroblasts of animal models of SSc." (PMID 29849001, 2018). "In systemic sclerosis, VDR was found regulates TGF-β Signaling." (PMID 33942213, 2021). "Expression of VDR is significantly lower in the peripheral blood lymphocytes of individuals with KD, in the epidermis of KLs, and in fibroblasts of patients with systemic sclerosis, another fibrotic condition." (PMID 32039229, 2019).
triple-negative breast carcinoma (6 papers, 2017 to 2025). An invasive breast carcinoma which is negative for expression of estrogen receptor (ER), progesterone receptor (PR), and human epidermal growth factor receptor 2 (HER2). "However, in triple-negative breast cancer models VDX-111 exerts its effects through a non-VDR-dependent mechanism demonstrating a lack of dependence on the VDR signaling axis." (PMID 38771847, 2024).
acute pancreatitis (5 papers, 2018 to 2024). An acute inflammatory process that leads to necrosis of the pancreatic parenchyma. "Our results suggest that allele T in the Taq-1 polymorphic site of the VDR gene is almost three times more frequent (OR = 2.61 (95% CI: 1.68–4.03, p < 0.0001) in acute pancreatitis patients than in alcohol-abuse controls." (PMID 29966312, 2018). "The observed genotype frequencies of Apa-1 (rs7975232), Bsm-1 (rs1544410), Fok-1 (rs2228570), and Taq-1 (rs731236) polymorphisms in the VDR gene were studied in 110 alcohol-abuse controls with diagnosed alcohol-abuse and 129 patients with acute pancreatitis." (PMID 29966312, 2018). "The aim of this study was to investigate the genetic association of the four different VDR polymorphisms (Apa-1, Bsm-1, Fok-1, Taq-1) with susceptibility to the development of acute pancreatitis compared to a control group of alcohol-abuse patients." (PMID 29966312, 2018). "Previous studies revealed that the VDR is expressed in the canine pancreas and serum VDR concentrations decreased in dogs with acute pancreatitis." (PMID 37808100, 2023). "A previous study showed that the serum VDR concentration is decreased in dogs with acute pancreatitis; however, it was unclear which organs contributed to the low serum VDR concentration." (PMID 37808100, 2023). "Several studies have been performed to investigate the association between vitamin D receptor (VDR) gene polymorphism and acute pancreatitis, but the results are inconclusive." (PMID 33879686, 2021). "Polymorphism Taq-1 occurring in the vitamin D receptor may have an impact on the development of acute pancreatitis due to the lack of the protective role of vitamin D." (PMID 29966312, 2018). "Therefore, polymorphisms in the vitamin D receptor gene may have an impact on the development of acute pancreatitis due to the lack of a protective role of vitamin D." (PMID 29966312, 2018).
Atrophy (5 papers, 2019 to 2024). Any weakening or degeneration, especially through lack of use. "As tenotomy itself induces muscle atrophy, VDR deficiency in the MPs may have caused certain pathological changes in the muscle." (PMID 38533539, 2024). "Therefore, further studies are required to confirm these findings and expand the knowledge in the direction of VDR polymorphism and the effects of eldecalcitol in preventing disuse muscle atrophy." (PMID 38115079, 2023). "We then assessed the effects of VDR-deficiency on simulated microgravity-induced atrophy." (PMID 35082348, 2022).
Cerebral ischemia (5 papers, 2019 to 2025). Restriction of arterial blood supply to the brain associated with insufficient oxygenation to support the metabolic requirements of the tissue. "Research indicates that following cerebral ischemia, there is a significant upregulation of VDR expression in microglia/macrophages surrounding the infarct area." (PMID 39944548, 2025). "The proportion of VDR+ microglia/macrophages within the infarct core also showed a comparable increase to that within the peri-infarct regions 3 days after cerebral ischemia." (PMID 36890539, 2023). "We found that vitamin D receptor (VDR) exhibited a predominant upregulation in peri-infarct microglia/macrophages following cerebral ischemia." (PMID 36890539, 2023). "Together, these results demonstrated that cerebral ischemia elicited prominent VDR upregulation in microglia/macrophages, suggesting a potential role of vitamin D signaling in the pathogenesis of acute ischemic stroke." (PMID 36890539, 2023). "Together, these findings indicated critical roles of VDR in restricting phenotypic switch of microglia/macrophages towards heightened inflammatory signatures after cerebral ischemia, particularly by limiting IFN signaling activation." (PMID 36890539, 2023). "Together, these findings indicated that VDR signaling in microglia/macrophages is essential for restraining brain injury and functional deficits following cerebral ischemia." (PMID 36890539, 2023). "For example, the VDR/ERK signalling pathway inhibited the apoptotic cascade in hippocampal CA1 neurons of global cerebral ischemia rats." (PMID 36159807, 2022). "Indeed, a considerably greater amount of IFN-γ was detected from microglia lacking VDR, indicating that VDR-deleted microglia served as an alternative source of IFN-γ following cerebral ischemia." (PMID 36890539, 2023). "In addition, this study focused on the actions of microglia/macrophage VDR in the acute phase of cerebral ischemia." (PMID 36890539, 2023). "Overall, our findings suggest that defective VDR signaling in microglia leads to its polarization towards a proinflammatory phenotype and increased cytokine production in response to cerebral ischemia, thereby aggravating poststroke neuroinflammation and disease outcome." (PMID 36890539, 2023). "Our study showed that VDR upregulation was more pronounced in microglia/macrophages than in other CNS cell types after cerebral ischemia, suggesting a potential endogenous protective mechanism against excessive neuroinflammation induced by acute ischemic stroke." (PMID 36890539, 2023). "To acquire mechanistic insights into how microglia/macrophages become more inflammatory in the absence of VDR following cerebral ischemia, we performed RNA-sequencing on microglia/macrophages isolated from control and Vdr-cKO mice undergoing sham or MCAO procedures." (PMID 36890539, 2023).
cystic fibrosis (5 papers, 2017 to 2025). Autosomal recessive disorder caused by pathogenic variants in the CFTR gene (cystic fibrosis transmembrane conductance regulator), which encodes a chloride and bicarbonate channel expressed in epithelial cells, and follow the diagnosis criteria. "In another study by P. McNally, they found that VDR and its agonists suppress proinflammatory cytokines production in cystic fibrosis." (PMID 37025056, 2023). "Other in vitro reports that have shown that A. fumigatus down regulated cystic fibrosis-patient derived epithelial cell and macrophage VDR." (PMID 29045457, 2017).
endotoxemia (5 papers, 2007 to 2025). "Furthermore, increased production of inflammatory cytokines to LPS, such as TNF-α and IL-1β, contributed to the failure of intestine barrier integrity in vitamin D deficient and VDR KO mice, leading to bacterial translocation, endotoxemia, and mortality." (PMID 36672703, 2023). "In accordance, VDR KO mice have shown to be more susceptible to LPS-induced endotoxemia, have higher expressions of inflammatory cytokines (e.g., TNF-α, IL-1a, IL-1β, IL-10, IL-21, and IFN-γ), and experience more weight loss, bleeding, ulceration, septic shock, and death compared to wild-type mice." (PMID 28066436, 2016). "It is likely that VDR KO mice were dying of severe bleeding and endotoxemia following perforation of the bowel induced by DSS." (PMID 17397543, 2007). "The early mortality of DSS treated VDR KO mice was likely due to perforation of the bowel and resulting endotoxemia." (PMID 17397543, 2007). "The increased lethality of VDR KO mice following DSS-administration may be a result of endotoxemia following perforation of the large intestine." (PMID 17397543, 2007). "All of the data support the hypothesis that the early mortality of the VDR KO mice treated with DSS is due to perforation of the gut and resulting endotoxemia." (PMID 17397543, 2007).
hemochromatosis (5 papers, 2004 to 2025). A disorder of iron metabolism characterized by a triad of HEMOSIDEROSIS; LIVER CIRRHOSIS; and DIABETES MELLITUS. "Previous studies measuring lead blood or bone levels in human populations identified polymorphisms in ALAD encoding δ-aminolevulinic acid dehydratase, associated with heme biosynthesis; VDR, which encodes the vitamin D receptor; and the hemochromatosis-associated gene HFE." (PMID 26859824, 2016). "Three polymorphic genes have been identified that can influence the bioaccumulation and toxicokinetics of lead in humans, the 6-aminolevulinic acid dehydratase (ALAD) gene, the vitamin D receptor (VDR) gene, and the hemochromatosis (HFE) gene." (PMID 21912545, 2011). "Although the specific genes remain to be fully characterized, polymorphisms in the vitamin D receptor (VDR), δ-aminolevulinic acid dehydratase (ALAD), and hemochromatosis (HFE) genes have all been implicated in differential lead absorption, retention, and excretion." (PMID 40457304, 2025). "Three genes are currently believed to play a role in lead neurotoxicity: the ALAD gene, which codes for δ-aminolevulinic acid dehydratase; the vitamin D receptor (VDR) gene; and the hemochromatosis gene coding for a defective protein known as HFE." (PMID 15198918, 2004).
hypogonadism (5 papers, 2015 to 2025). A disorder characterized by decreased function of the gonads. "Cyp27b1 null mice and mice that lack the vitamin D receptor have shown hypogonadism, arrested follicular development, prolonged estrous cycles, and hypoplastic uteri." (PMID 25879830, 2015). "However, even if the correlation between vitamin D and hypogonadism is not entirely clear, it must be considered that the expression of hydroxylases (CYP2R1 and CYP27B1) and VDR in testis tissue also represents a further indication of the importance of the testicles in the metabolism of vitamin D." (PMID 34067977, 2021).
lymph node metastasis (5 papers, 2017 to 2024). "However, a higher nuclear VDR-IRS of normal lobules was associated with increased odds of lymph node metastases in both the investigated models." (PMID 39411136, 2024). "Of note, VDR upregulation strongly correlated with negative symptoms, negative lymph node metastasis and a negative resection margin." (PMID 28256614, 2017). "Therefore, it is reasonable to infer that in tumors with lymph node metastasis, owing to the reduced or absent VDR expression, although with a high level of 1,25(OH)2D, they cannot sufficiently bind to VDR and exert its anti-tumor effects." (PMID 37991208, 2024).
malnutrition (5 papers, 2014 to 2024). Inadequate nutrition resulting from poor diet, malabsorption, or abnormal nutrient distribution. "This nutritional deficiency may be attributed to the vitamin D receptor (VDR), which is essential for immunomodulatory activity by regulating antigen-presenting cells and T-cell function." (PMID 39539349, 2024).
metastatic melanoma (5 papers, 2012 to 2024). A melanoma that has spread from its primary site to another anatomic site. "This is the only report we are aware of that attempted to correlate VDR polymorphisms with outcomes in metastatic melanoma patients." (PMID 25563456, 2014). "Alternatively, the high-risk VDR genotype may represent a biomarker for worse survival in metastatic melanoma, and thus represents an additional prognostic factor that should be controlled for in trials of advanced disease." (PMID 25563456, 2014). "For example, miRNA-125b is involved in the regulation of vitamin D receptor (VDR), and in the resistance of 1,25-dihydroxyvitamin D3, a potential therapy for metastatic melanoma." (PMID 34198989, 2021). "Overall, expression of VDR decreased from benign nevi to metastatic melanoma and further decreased in metastasizing primary tumors." (PMID 34692525, 2021). "Interestingly, the expression of VDR as wells as of RORs was related to the HIF1α activity, which also affected FoxP3 expression in metastatic melanoma." (PMID 34692525, 2021). "Therefore, the expression pattern of human NDRG2, VDR, NSD1, CTCF and SRC genes in several human metastatic melanoma cell lines in comparison to primary melanocytes were analyzed at mRNA level by RT-qPCR methodology." (PMID 22984562, 2012).
neuropathy (5 papers, 2018 to 2025). A disorder affecting the nervous system that manifests with pain, tingling, numbness, and/or muscle weakness. "VDR is up-regulated in T1DM with mild neuropathy and further up-regulated in T1DM with severe neuropathy in comparison with the epidermis, stratum basale, stratum spinosum, overall microvessels, endothelium and pericytes." (PMID 32538430, 2020). "Many of the processes in which VDR is involved, such as reduction of oxidative stress, neuroprotection, anti-inflammatory processes, and insulin control, are shared with SIRT1 and downregulation of both genes could contribute to the onset of neuropathy." (PMID 39976627, 2025).
parasitemia (5 papers, 2012 to 2023). "VDR has been associated with the severity of parasitemia and gametocytemia clearance in Plasmodium vivax malaria infections." (PMID 38099246, 2023). "IL6, together with IL12 and VDR, have been associated with reduced parasitemia, its severity and gametocytemia clearance in P. vivax-exposed individuals." (PMID 29868512, 2018). "VDR has also been implicated in macrophage responses to parasitic infections." (PMID 30897154, 2019). "Most B6 and B6.VDR−/− mice died within 9–10 days of infection and showed similar parasitemias, clinical scores, hemoglobin levels and body temperatures." (PMID 22242171, 2012). "Further study is required to discern the role of VDR during parasitic infections." (PMID 30897154, 2019).
parathyroid hyperplasia (5 papers, 2012 to 2022). A hyperplasia that involves the parathyroid gland. "Reduced circulating 1,25D and parathyroid VDR expression play a key role in the progression of parathyroid hyperplasia." (PMID 35208186, 2022). "Research demonstrating the importance of the hypermethylation of CaR and VDR in carcinogenesis makes the CaR and VDR genes interesting candidates for promoter methylation analysis in parathyroid hyperplasia." (PMID 23094155, 2012). "In addition, parathyroid gland hyperplasia leads to reduced expression of the VDR, CaSR and FGF23 receptor complex in experimental SHP models and human parathyroid samples." (PMID 35208186, 2022). "Even in the early stages, there is a decrease of the calcium sensor receptor and vitamin D receptor, making parathyroid cells unresponsive to ambient calcium and vitamin D levels, resulting in a proliferative state of parathyroid cells and inducing parathyroid hyperplasia." (PMID 33579041, 2021).